MTOR (mechanistic target of rapamycin kinase)
Diseases named in the same sentence as MTOR in open-access papers (continued):
Sharing a sentence is not in itself a finding about the gene and the disease.
melanoma (continued). "Here, we demonstrate that genetic or therapeutic targeting of the PREX2/RAC1/p110β pathway can substantially enhance responses to MAPK targeting in BRAF-mutant melanoma both in vitro and in vivo, presumably through suppression of AKT/mTOR driven cell-cycle progression." (PMID 39636745, 2025). "The presence of primary or acquired resistance in melanomas limits the therapeutic efficacy of binimetinib as a monotherapy, as MEK inhibition can lead to the activation of compensatory intracellular signaling pathways, such as the PI3K/AKT/mTOR cascade." (PMID 41373567, 2025). "In melanoma, ARS may regulate the proliferation, migration, and invasion of uveal melanoma cells by activating the PI3K/AKT/mTOR pathway, suggesting that ARS could be a novel tumor factor." (PMID 41373571, 2025). "In addition, current and ongoing clinical trials have focused on agents targeting the PI3K/AKT/mTOR pathway in metastatic and BRAF-mutant melanoma." (PMID 40399946, 2025). "Additionally, resistance mechanisms include the PI3K/AKT/mTOR pathway, which is dysregulated in 22% of BRAF inhibitor-resistant melanomas characterized by increased expression of the AKT protein." (PMID 39941158, 2025). "Principal oncogenic signal transduction in melanoma often engages Ras/MAPK activation and can co-involve, or recruit, dysregulated PI3K/AKT/mTOR signaling that can serve as a source of resistance to MAPK inhibition, including in the case of human and canine MM." (PMID 40723239, 2025). "Studies have shown that the activation of mTOR prevents cellular senescence caused by BRAF mutations, but this pathway does not appear to lead directly to the development of malignant melanoma." (PMID 39161800, 2024). "To determine whether USP22 activates the PI3K/Akt/mTOR pathway via SIRT1‐mediated PTEN deacetylation, we used siRNA to silence the expression of SIRT1 in USP22‐overexpressing melanoma cells." (PMID 39135915, 2024). "CSC-dependent melanoma progression is mediated by MAPK/ERK and PI3K/Akt/mTOR pathways." (PMID 38334632, 2024). "Our previous studies on mTOR kinase inhibitors indicated that even nanomolar concentrations of everolimus, in combination with the MEK kinase inhibitor AS-703026, strongly activated the apoptosis process in melanoma cells." (PMID 39596342, 2024). "We tested three melanoma cell lines, primary (VGP) WM3211 and metastatic: Me15392 and MEWO, for 25μM concentrations of chloroquine and mTOR inhibitor everolimus in concentrations ranging from 20 nM to 25 μM and 50 μM concentrations of rapamycin alone and in combination with chloroquine." (PMID 39596342, 2024). "Rapamycin (Sirolimus), the mTOR inhibitor used in both humans and canines to inhibit cell proliferation in various cancers, including melanoma, has shown similar IC50 values in inhibiting melanoma cell growth in both species." (PMID 39408717, 2024). "In melanoma, the overexpression of ARG2 in Treg increases their accumulation in tissues and suppressive capacity for the inhibition of mTOR signaling by the modulation of the PI3K/AKT/mTOR signaling pathway." (PMID 39337272, 2024). "By affecting the PI3K/AKT/mTOR pathway and the expression of the downstream transcription factor HIF-α, which play vital roles in tumors, celastrol has demonstrated its ability to impede the growth of B16-F10 melanoma cells." (PMID 38771435, 2024). "Knowing that melanoma tumors at the leptomeninges rarely respond to MAPK inhibitor therapy and grow rapidly, we examined the spatial expression of MAPK targets and targets of mTOR in the leptomeningeal tissues." (PMID 38866016, 2024). "Although the characterization of Fyn-stimulated CD133/PI3K/mTOR is not described in human melanoma, the mechanism of Fyn-stimulated CD133 signal to the PI3/AKT axis seems to be a general mechanism in solid tumors." (PMID 38334632, 2024).
melanoma (continued). "Combinatorial and/or sequential inhibition of CD133 signaling to PI3K/AKT/mTOR and PI3K/RAS/RAF/MEK/ERK pathways, after first-line immunotherapy, may extend the anti-tumor response for melanoma patients." (PMID 38334632, 2024). "This agrees with current clinical practice which uses mTOR and BRAF inhibitors as first-line therapy for kidney cancer and melanoma, respectively, since the c-Met/mTOR axis is frequently altered in kidney cancer while BRAF mutations are the main genetic drivers of melanoma." (PMID 38041118, 2023). "Taken together, our findings indicate that mTOR, bile acid metabolism, and peroxisome metabolic pathways are coordinately dysregulated and highly upregulated in the CD8+ TILs of melanoma and SCC patients, impacting the capacity of the host immune system to suppress and eradicate tumor cells." (PMID 38023136, 2023). "Later, the downregulation of p-AKT, p-mTOR, and p-P70S6K were obtained in A375 and BRAF mutation-negative melanoma cell line C8161 after treatment with curcumin." (PMID 36829966, 2023). "Furthermore, a reduction in actin intensity in p38–high cells strongly suggests a role of mTOR in regulating actin and a remodeling in the NRAS-mutant melanoma cells." (PMID 36765834, 2023). "In addition to MAPK signaling, we examined the depigmentation effect of ITA and DMI through PI3K/AKT/mTOR axis and GSK3β signaling in α-MSH-treated B16 melanoma cells." (PMID 35807430, 2022). "Interestingly, the simultaneous activity of the PI3K/AKT/mTOR and MEK/ERK pathways is characteristic for many tumor cells, including melanomas." (PMID 35327461, 2022). "Furthermore, NPC-402 downregulated AKT survival signaling pathway albeit upregulated the expression of p-mTOR, corroborating with growth inhibitory effects of NPC-402 in B16F10 melanoma cells." (PMID 35982963, 2022). "Since both the activation of mTOR and NAD metabolism via NAMPT are involved in the therapeutic resistance of melanoma to BRAFi/MEKi, an outstanding question is whether in this context these two these two key molecular pathways are functionally interconnected." (PMID 36077374, 2022). "Thus, EVs released by the metastatic melanoma cells stimulate the growth of the normal keratinocytes via the activation of EGFR and the PI3K/AKT/mTOR and MEK/ERK intracellular signaling pathways." (PMID 35327461, 2022). "Specifically, we applied a mRNA panel consisting of KI67 (indicative of cell proliferation), POLR2A, BRCA1, MTOR, NCOA2, and NCOA3 to highly scattering and autofluorescent human melanoma skin biopsy FFPE tissues obtained from and characterized by the UCI Dermatopathology Center." (PMID 35013281, 2022). "Moreover, human melanomas with attenuated IFN-γ signaling or ICB resistance exhibit reduced expression of T cell signature genes and alteration of target genes downstream of mTOR and JAK1/2 pathways, suggestive of their activation." (PMID 36008408, 2022). "However, a later study demonstrated that B7-H3 overexpression enhanced proliferation and glycolytic capacity in melanoma cells, with reduced sensitivity toward dacarbazine, a MAPK- and AKT/mTOR-targeting small-molecule inhibitor." (PMID 36284349, 2022). "Another effective strategy for treating melanoma may be the combination of 17AAG, an HSP90 inhibitor with NVP-BEZ235, a PI3K/mTOR inhibitor." (PMID 35163615, 2022). "Nonetheless, we found that treatment with nalfurafine hydrochloride did not activate but inhibit the mTOR pathway in B16F1 melanoma cells." (PMID 36611940, 2022). "Collectively, these results establish that augmentation of mTOR pathway is a major upstream regulator of JAK1/2 activation in melanoma cells lacking functional IFN-γ signaling." (PMID 36008408, 2022). "However, activation of numerous tyrosine kinase receptors expressed on both melanoma and TNBC tumors leads to activation of both the PI3K/AKT/mTOR and MAPK pathways." (PMID 35806358, 2022).
melanoma (continued). "In the melanoma setting, BRAF inhibitors induce ATF4 translation through two independent signaling pathways: they trigger GCN2 kinase autophosphorylation that activates the canonical ISR, but also can sustain mTOR- and eIF4B-driven ATF4 translation." (PMID 35912100, 2022). "Instead, the TAAR6 coexpressed gene cluster in melanoma is enriched in pathways “Inflammatory mediator regulation of TRP channels” representing processes in nociceptive dorsal root ganglion (DRG) neurons, and “mTOR signaling pathway”." (PMID 35053262, 2022). "In contrast, these cells were more sensitive to mTOR pathway inhibition than control cells, which suggests that acidification-induced melanoma phenotype exhibits preference towards mTOR rather than ERK signaling." (PMID 33918883, 2021). "Together, these data suggest that neither MYC nor the mTOR pathway is a key driver of enhanced mitochondrial metabolism following CDK4/6 inhibition in melanoma cells." (PMID 33572972, 2021). "To date, there has been no report of mTOR inhibitors used clinically in canine melanoma treatment and overall, rapalog clinical trials are currently in their infancy for the treatment of cancer-bearing canine patients." (PMID 34895222, 2021). "In addition, AKT/mTOR signaling and MAPK signaling were inhibited by JIB extract to suppress melanoma cell growth and proliferation." (PMID 33390784, 2021). "Thus, in contrast to combined inhibition of PI3K and MEK, mTOR inhibition alone leads to the sustained suppression of RAS and PI3K pathways and tumor-cell growth in transplanted melanomas." (PMID 34331013, 2021). "Interestingly, though, Salmonella treatment overturned the enhanced Akt/mTOR activity and increased SNAI1 expression in Akt-transfected melanoma cells." (PMID 34207850, 2021). "In all melanoma cell lines, a statistically significant difference in non-glycolytic acidification was detected between mTOR inhibitor treatment and control (p < 0.001 to p < 0.0001)." (PMID 34895222, 2021). "Interestingly, this dual effect has also been shown in melanoma cells, where abrogation of LKB1 expression cooperates with V600EBRAF to activate mTOR." (PMID 34204950, 2021). "A recent report in a melanoma patient experiencing kidney allograft rejection following PD‐1 blockade suggests that mTOR inhibitors can increase tolerogenic mechanisms against nontumoral tissue at the same time preserving the activity of checkpoint inhibitors." (PMID 34185403, 2021). "In addition, IPA analysis revealed that actin cytoskeleton, PI3K/mTOR signaling, and EIF2 function were the most consistently deregulated pathways in the treated melanoma cells." (PMID 33672955, 2021). "Given that Salmonella influences gene expression in tumors by modulating Akt/mTOR and MAPK signaling, we examined the effect of Salmonella treatment on the expression of SNAI1 in a panel of melanoma cell lines, as SNAI1 was known to be regulated, in part, by Akt signaling." (PMID 34207850, 2021). "As in vitro proof of principle with canine melanoma cell lines of differing basal ERK and AKT activity, synergistic growth inhibitory effects are observed by combining an MEK inhibitor with a dual PI3K/mTOR inhibitor." (PMID 34822659, 2021). "Tegaserod has proven effective in inducing apoptosis and limiting tumor and metastasis development in mice inoculated with B16F10 melanoma by decreasing the expression of CD4+CD25+ T cells and hindering the PI3K/Akt/mammalian target of the rapamycin (mTOR) signaling pathway." (PMID 34068618, 2021). "Collectively, these data suggest that combining mTOR inhibitors and/or MDM2/MDM4 inhibitors might overcome the intrinsic resistance to CDK4/6 inhibitors in melanoma." (PMID 34071228, 2021).
melanoma (continued). "In melanoma, multiple signaling pathways are dysregulated, involving oncogenes and tumor suppressors (i.e., PI3K/AKT/mTOR, MAPK, RAS/MEK/ERK, BRAF, and CDK); the multiple dysregulation of these signaling pathways favors tumor invasiveness, progression, drug resistance, and recurrence." (PMID 32793477, 2020). "Also, data from other groups showed that B7-H3 knockdown resulted in more sensitive of melanoma cells to small-molecule inhibitors targeting MAPK and AKT/mTOR pathways." (PMID 33426073, 2020). "Our hypothesis for this study suggested that CAP and SN co-effectively blocked the classical PI3K/mTOR and EGF/MEK survival pathways, which will eventually lead to the activation of autophagy in G-361 human melanoma." (PMID 32178401, 2020). "Treating 501Mel cells with the mTOR pan-inhibitor Torin-1 (1 μM, 3 hours) resulted in increased nuclear localization of the endogenous TFEB protein, suggesting that mTOR activity contributes to the cytoplasmic retention of TFEB in melanoma cells." (PMID 32881934, 2020). "Furthermore, we would like to know how Polyphyllin I regulated melanoma cells apoptosis and autophagy, PI3K/Akt/mTOR signaling pathway activator IGF-1 was used." (PMID 32733943, 2020). "It has been previously reported that acacetin, isoangustone A, sulforaphane and tryptanthrin inhibited melanoma cell proliferation and tumor growth, and induced cell cycle arrest and apoptosis by directly or indirectly targeting PI3K/AKT/mTOR signaling pathways." (PMID 32962182, 2020). "Melittin can also induce caspase-dependent apoptosis in melanoma cells also by displaying a downregulation of phosphoinositide 3-kinase (PI3K), protein kinase B (AKT), mammalian Target of Rapamycin (mTOR) and 5’ adenosine monophosphate-activated protein kinase (MAPK) signaling pathways." (PMID 33142794, 2020). "Apoptosis dependent on the Akt-Ser473 inhibition and downstream target proteins by CDPs in our melanoma model indicates the participation of the mTORC1 and mTORC2 complexes in blocking the PI3K/Akt/mTOR signaling pathway; in agree with recent findings described in HeLa cells." (PMID 32793477, 2020). "In melanoma, most anti-cancer therapy and treatment approaches commonly targeted serine/threonine protein kinase inhibitors, particularly those involved in the Ras/Raf/MEK/ERK and PI3K/PTEN/Akt/mTOR signaling pathways." (PMID 33260329, 2020). "In melanoma B16 tumors, a subpopulation of PD-1 expressing cancer cells were identified to modulate downstream mTOR signaling and promote tumorigenesis independent of adaptive immunity, in an in vivo mouse model lacking an adaptive immune system." (PMID 33193345, 2020). "Moreover, HOTAIR facilitates the growth and metastasis of melanoma cells via competitively binding to miR-152-3p and activating the downstream PI3K/Akt/mTOR signaling pathway." (PMID 33346222, 2020). "Further studies have found that in melanoma cells treated with BRAF inhibitor, the downregulation of transcription factor FOS related antigen-1 (FRA1) activates multiple signaling pathways, among which the PI3K/AKT/mTOR pathway plays a major role." (PMID 32175074, 2020). "Therefore, targeting PI3K/AKT/mTOR and MAPK pathways simultaneously can be a promising strategy to overcome chemoresistance of melanoma." (PMID 30866426, 2019). "Although the mTOR pathway can be activated in the majority of melanomas, mTOR inhibitors have not been proven effective in this clinical setting." (PMID 31624262, 2019). "A PI3K/mTOR inhibitor, GSK2126458A, given in combination with dabrafenib efficiently counteracted the stimulating effects of a BRAF inhibitor on invasiveness, and VEGF-A and MMP-9 secretion in A375R melanoma cells resistant to darafenib." (PMID 31295843, 2019).
melanoma (continued). "Regarding KEGG pathway functions associated with the feather follicles, significant differences were found in the following signaling pathways: calcium, PI3K-Akt, mTOR, cAMP, MAPK, Wnt, cGMP-PKG, Jak-STAT and adrenergic signaling in cardiomyocytes, melanogenesis, tyrosine metabolism, and melanoma." (PMID 31693656, 2019). "Investigated was also the effect of protein kinases’ inhibitors: AKT – MK-2206, MEK – AS-703026, PI3K – LY294002 and ERK1/2 – U126 and mTOR – everolimus in a single mode, and their combinations on caspase-3 activation and proliferation in WM266–4 and WM115 melanoma cell lines." (PMID 30848427, 2019). "Our results showed that BV and melittin potently suppress the growth and migration of melanoma cells via dual inhibition of PI3K/AKT/mTOR and MAPK pathways, suggesting that melittin could be a promising chemotherapeutic agent for malignant melanoma treatment." (PMID 30866426, 2019). "Indeed, the rescue effect of magnolol upon Akt activation was mediated through increased p‐Akt, p‐mTOR, and p‐ERK levels in melanoma cells." (PMID 30793515, 2019). "Notably, no secondary mutations in RAS, MEK, and ERK that could rebound BRAF–MEK–ERK signaling were found in PLX4720-treated TFEBS142E tumors, and no concurrent activation of the Akt–mTOR signaling pathway, previously implicated in melanoma resistance, was detected in PLX4720-treated tumors." (PMID 30979895, 2019). "Additionally, the significant enrichment of melanoma EMT-involved pathways, such as the MTORC1_SIGNALING and PI3K_AKT_MTOR_SIGNALING hallmarks in these CTC fractions, suggests an invasive transcriptional programming of ABCB5 CTCs." (PMID 30769764, 2019). "To elucidate the molecular mechanism responsible for the malignant melanoma inhibitory effect of melittin, we confirmed whether melittin affects PI3K/AKT/mTOR and MAPK signaling." (PMID 30866426, 2019). "Current results clearly show that the nanomolar concentration of the mTOR inhibitor everolimus in combination with the inhibitor of MAP kinase (AS-703026) or AKT kinase (MK-2206) is effective in inducing apoptosis and reducing proliferation of melanoma cells." (PMID 30848427, 2019). "Our results demonstrated that bornyl cis-4-hydroxycinnamate is a potentially useful agent that inhibits melanoma cell migration and invasion, and altered melanoma cell metastasis by reducing MMP-2 and MMP-9 expression through inhibition of the FAK/PI3K/Akt/mTOR, MAPK, and GRB2 signaling pathways." (PMID 30042328, 2018). "Additionally, all IDTCs had increased activation of MAPK, AKT, and mTOR pathways, as previously demonstrated for the BRAF mt melanoma IDTCs." (PMID 29492189, 2018). "We have found that BRAF melanoma cells exposed to a low extracellular pH medium acquired a resistance to both BRAF and MEK inhibitors but were still sensitive to the inhibition of the AKT/mTOR pathway induced by RAD001." (PMID 30544808, 2018). "Targets of the PI3K pathway were also found to be significantly dephosphorylated in cells where BAG3 was silenced such as AKT, mTOR and the p70S6K that also were found to be interesting targets to overcome acquired resistance to to BRAFV600E inhibition in melanoma." (PMID 29113311, 2017). "In human melanoma A375 and C8161 cell lines, apigenin effectively suppressed cell proliferation, migration and invasion and induced G2/M phase arrest and apoptosis via decreasing p-ERK1/2, p-AKT and p-mTOR." (PMID 29034071, 2017). "mTOR phosphorylation in Ser2448 was found to be reduced in PC-E and PC-L cells as compared to MSC, further confirming increased autophagic flux in differentiating melanoma cells as compared to melanosphere cells." (PMID 28617309, 2017). "Combined targeting of the MEK/ERK and PI3K/mTOR pathways had antitumor activity and might serve as a therapeutic option in the treatment of NRAS mutant melanoma." (PMID 29285234, 2017).